IL10 (interleukin 10)
Diseases named in the same sentence as IL10 in open-access papers (continued):
Sharing a sentence is not in itself a finding about the gene and the disease.
Stroke (continued). "Because an imbalance between pro-inflammatory and anti-inflammatory cytokines can significantly affect stroke outcomes, an IL-10 increase driven by Cerebrolysin may foster a more balanced immune response and support tissue repair." (PMID 40362194, 2025). "Elevated IL-10 may indicate a protective, anti-inflammatory response, which is important for stroke management and prognosis." (PMID 40142325, 2025). "Some studies propose that IL-10 or IL-10/IL-6 ratios could serve as biomarkers to predict post-stroke complications, including infections or hemorrhagic conversion." (PMID 40869247, 2025). "Since Tregs are a source of IL‐10, which increases during the chronic phase beginning 2 weeks after stroke, it suggests that Tregs may influence NSC activity and contribute to stroke recovery." (PMID 39878387, 2025). "In addition, the level of IL‐10 was significantly elevated after stroke, and low IL‐10 levels were related to poor outcomes of stroke." (PMID 38506071, 2024). "In addition to the anti-inflammatory roles of IL-10 in the inflammatory response after stroke, IL-10 is also a negative regulator of pro-inflammatory cytokines TNF-α, IL-1β and IL-6." (PMID 38421829, 2024). "Furthermore, we observed noteworthy disparities in the plasma levels of IL-2, IL-4, IL-6, IL-10, TNF-α, and INF-γ between patients devoid of risk factors and those presenting with comorbid risk factors associated with stroke." (PMID 38287458, 2024). "Additionally, we explored the potential of the anti-inflammatory marker interleukin-10 (IL-10) to provide a balanced perspective on the immune response following stroke." (PMID 37752283, 2023). "Studies in models of stroke also support the importance of IL-10 as a mediator of Breg activity." (PMID 38269112, 2023). "IL-10 levels were increased prominently at 24-h of stroke with 12/15-LOX inhibition." (PMID 37822799, 2023). "After stroke, the levels of inflammatory cytokines in patients with cognitive abnormalities are higher than those in patients with normal cognition, such as IL-1β, IL-6, IL-8, IL-10, and IL-12, leading to nerve damage and decreased cognitive function." (PMID 37397457, 2023). "More recently, Piepke and colleagues reported that IL-10-mediated IL-17 production is a key factor that limits stroke lesions, and may be a potential target for stroke management." (PMID 37398661, 2023). "To determine whether inhibition of IL-10 in astrocytes also affects neuronal apoptosis after stroke, we detected the expression of IL-10Rα in neurons by immuno-fluorescence." (PMID 37196130, 2023). "IL-10 and interferon-gamma (IFN-γ) were associated with the development of arrhythmia after CABG surgery, and in a cohort study, the second was considered a marker for stroke prediction and all-cause mortality in patients with new-onset AF." (PMID 36834735, 2023). "The protective effect of IL-10 on stroke is mainly achieved by inhibiting inflammatory reactions." (PMID 35173738, 2022). "Additionally, IL-10 inhibits IL-2 activity, and has been shown in numerous studies to be increased after stroke or TBI." (PMID 35745576, 2022). "In addition, IL-10 treatment can effectively down-regulate the up-regulated pro-inflammatory signals in acute ischemic lesions after stroke, and can provide neuroprotection for ischemic stroke." (PMID 35173738, 2022). "One explanation for this may be that IL-10 levels peak early after a stroke, so the increase may have been missed." (PMID 36430226, 2022). "Beyond IL‐10, the development of poststroke infections also correlates with lower TNF‐α levels and the consequent decrease in the TNF‐α/IL‐10 ratios at day 2 after stroke, this latest supporting a role of the Th1/Th2 shift in patients suffering from such complications." (PMID 35971650, 2022). "IL-10 is a key neuroprotective cytokine regulating neuroinflammation after stroke." (PMID 36247760, 2022).
Stroke (continued). "Moreover, low IL-10 levels were related to poor stroke outcomes and a delayed, exacerbated inflammatory response that was alleviated by IL-10 administration after pMCAO." (PMID 35173738, 2022). "In addition, we previously reported using whole genome sequencing that intracerebroventricular injection of IL-10 is sufficient to modulate the neuroinflammatory response after experimental stroke." (PMID 36512388, 2022). "Lower IL-10 levels are related to one of increased risks in stroke." (PMID 35795571, 2022). "IL-10-secreting CD4+ T cells induced by nasal MOG reduce injury following stroke." (PMID 35173738, 2022). "These methods of targeting IL-10 to prevent recurrence of stroke may be realized in the interventional treatment of stroke." (PMID 35173738, 2022). "Increased β2-adrenergic signaling after an experimental stroke typically inhibits microglial/monocyte-derived macrophage response and reduces the upregulation of pro-inflammatory and anti-inflammatory cytokines (TNFα and IL-10)." (PMID 36569944, 2022). "IL-10 is generally known as an anti-inflammatory cytokine that exerts a plethora of immunomodulatory functions during an inflammatory response and is particularly important during the resolution phase of stroke." (PMID 35207221, 2022). "DMOG upregulated IL-10 protein expression and mRNA levels 7 days post-stroke." (PMID 34205911, 2021). "Although IL-10 and IL-17A have opposing effects on stroke outcome, it is largely unknown whether these two cytokines interact." (PMID 34772416, 2021). "Serum IL-10 levels decreased with the increasing severity of stroke (evaluation by NIHSS score)." (PMID 34336007, 2021). "In this study, we tested whether the anti-inflammatory cytokine IL-10 controls the early IL-17A response in T cells following experimental stroke." (PMID 34772416, 2021). "Interestingly, in CD4+ T cells, we identified two different IL-10+ subpopulations that peak at different timepoints following stroke." (PMID 34772416, 2021). "The neuroprotective role of IL-10 in an experimental mouse stroke model had been verified." (PMID 34336007, 2021). "NSE and IL-10 were increased in stroke vs. control and correlated with neurological deficits." (PMID 33115334, 2021). "Thus, Tregs-derived anti-inflammatory factors, including transforming growth factor-beta (TGF-β) and interleukin-10(IL-10), were reduced after stroke." (PMID 34248961, 2021). "Our results, in line with previously published studies, suggest that metformin-inhibited microglial activation and enhanced IL-10 production may contribute to the beneficial effects of metformin therapy on stroke outcome." (PMID 33915857, 2021). "During the early hours after the onset of stroke, there are increments of various cytokines such as interleukin-1 beta (IL-1β), interleukin-1 receptor antagonist (IL-1ra), interleukin-6 (IL-6), IL-8, IL-10, and tumor necrosis factor alpha (TNF-α)." (PMID 34072449, 2021). "Salivary TNF-α, IL-6, and IL-10 may be potential non-invasive biomarkers that distinguish stroke patients from controls with high sensitivity and specificity." (PMID 34433866, 2021). "The mRNA level of anti-inflammatory IL-10 was reduced at 1, 3, and 7 days after stroke as well." (PMID 32010477, 2020). "However, the increase in IL-10 expression appears strongly but transiently as early as 6 h post-stroke." (PMID 32867781, 2020). "During the subacute phase of stroke, two anti-inflammatory cytokines, IL-10 and TGF-β, from astrocytes can reduce the number of activated microglia, macrophage, and monocytes, which may be related to improved axonal repair." (PMID 33042113, 2020). "However, we provide a new insight into monocytic function post-stroke since we can report that a differential regulation of HLA-DR and PD-L1 was found depending on the IL-10 production of monocytes." (PMID 33329318, 2020). "IL-10 levels are decreased within 24 hours of stroke and increased over 72 hours post-stroke." (PMID 32244523, 2020).
Stroke (continued). "However, the number of T cells producing either pro-inflammatory cytokine IFN-γ or anti-inflammatory cytokine IL-10 significantly decreased at day 5 post-stroke [median (IQR) 0.65 (0.46–0.98)] vs. admission day." (PMID 32719588, 2020). "Since the regulation of myeloid cells during stroke-induced immune alterations is unknown, we conducted the present study to analyze the effects of stroke on MDSCs and IL-10+ monocytes, which are known to exert immunosuppressive properties." (PMID 33329318, 2020). "Interestingly, levels of IL-10, generally regarded as an anti-inflammatory cytokine, were robustly but transiently increased at 6 h after stroke; however, this high level of expression continued to 48 h in the rhFGF21 treatment groups." (PMID 32867781, 2020). "Moreover, IL-10+ monocytes showed a significantly higher expression of HLA-DR on days 1 and 5 after stroke than did IL-10− monocytes (p < 0.0001)." (PMID 33329318, 2020). "Similar to Tregs, Bregs that secrete IL-10 also protect against I/R injury, but further studies are needed to confirm whether these Bregs are released by the spleen after stroke." (PMID 30700305, 2019). "As seen for IL-37, several other anti-inflammatory markers, namely Foxp3 (P = 0.012), Ym1 (P = 0.006), Il-10 (P = 0.018), Il-13 (P = 0.002) and Tgfb (P = 0.008) were up to 3-fold increased in the ischemic hemisphere following stroke in IL-37tg compared to WT mice." (PMID 31061403, 2019). "IL-10 is an important component of the endogenous repair mechanism after stroke." (PMID 30700305, 2019). "Our study suggests that with proper timing, IL-10 treatment may be a very effective strategy to combat brain damage after stroke." (PMID 31801113, 2019). "However, Nakajima and colleagues showed that rats which were treated intravenously with MSCs + IL-10 either immediately or at 3 h after a stroke had improved motor outcomes on the rotarod task." (PMID 30611291, 2019). "The IL-10 levels in the brain and spleen increase after stroke." (PMID 30700305, 2019). "In addition, Lactadherin treatment also significantly increases anti-inflammatory factor IL10 expression in IBZ compared to stroke mice treated with PBS or BDMPs, respectively." (PMID 31993045, 2019). "Adoptive transfer of IL-10-secreting cells is widely used for the treatment of experimental stroke." (PMID 30700305, 2019). "Interestingly, this is accompanied by the reduction of IL-10 in the peripheral blood of patients in the acute phase of the stroke within the first 12–24 h." (PMID 31514749, 2019). "Phagocytosis of debris and dying cells promotes upregulation of anti-inflammatory mediators such as TGF-β and IL-10 in activated macrophages and monocytes, which help to dampen Th1 and Th2 responses, promote Treg development, and ultimately resolve post-stroke neuroinflammation." (PMID 29895321, 2018). "Additionally, we found that the concentrations of TNF-α, IL-6, IFN-r and IL-10 were significantly increased post-stroke." (PMID 30013463, 2018). "However, after 4 days, the IL-10−/− mice have higher levels of proinflammatory molecules that persist through the end of the first week after stroke." (PMID 28659854, 2017). "Indeed, iNKT cell activation was positively correlated with IL-10 production in patients with stroke, and this rapid and sustained elevation of plasma IL-10 was exacerbated in patients who developed infections after stroke." (PMID 28154551, 2017). "Among the cytokines known to be associated with inflammation in stroke, interleukin-1 (IL-1) and TNF-α were reported to aggravate cerebral injury; in contrast, interleukin-6 (IL-6), interleukin-10 (IL-10), and transforming growth factor-β (TGF-β) were shown to be neuroprotective." (PMID 29090015, 2017). "Stroke patients were found to present with a rapid increase in plasma cytokines resulting in a low ratio of pro-inflammatory tumor necrosis factor alpha (TNFα) to anti-inflammatory interleukin (IL)-10, preceding the appearance of infection." (PMID 28154551, 2017).
Stroke (continued). "Moreover, serum levels of TNF-α and IL-6 decreased, whereas IL-10 increased in stroke patients between day 1 and day 3 (all p < 0.05)." (PMID 27682880, 2017). "Previous reports have shown that TNF-α, IFN-γ, IL-6, IL-17, IL-23, and some monocytes are detrimental in the pathologic process of stroke, whereas Treg cells, IL-4, IL-10, and TGF-β are major cerebroprotective modulators of post-ischemic inflammatory brain damage." (PMID 27682880, 2017). "Interestingly, we did not observe an effect of BML‐111 treatment on anti‐inflammatory cytokines IL‐10 and IL‐4 at 1 week post‐stroke, despite increased CD163+ microglia/macrophages." (PMID 28523230, 2017). "Therefore, our data support the notion that IL-10 production after stroke is critical in the impairment of host antibacterial defense and suppression of the systemic immune system, potentially via a mechanism that involved the activation of iNKT cells." (PMID 28154551, 2017). "We next examined whether plasma levels of IL-10 at Admission in stroke patients is a potential predictor of infection development." (PMID 28154551, 2017). "The serum levels of TNF-α, CRP, TGF-β, IL-4, IL-6, IL-10, IL-17, and IL-23 were all increased on days 1, 3, and 7 after stroke when compared with levels in the control group (all p < 0.05); however, the content of IFN-γ was lower in stroke patients than in controls at each time point (p < 0.01)." (PMID 27682880, 2017). "Nonetheless, the plasma level of IL-10 was significantly higher in patients with stroke who later developed infections, potentially suggesting the circulatory level of IL-10 at stroke onset has the potential to serve as a predictive biomarker for poststroke infection." (PMID 28154551, 2017). "However, the confirmation that the increased peripheral IL-10 level after stroke was attributed by iNKT cells will require flow cytometric analysis of intracellular cytokine production of live iNKT cells in future studies." (PMID 28154551, 2017). "In contrast, B cells may be neuroprotective as B cell deficient mice tended to have increased infarct volume, suggesting an immune regulatory role of B cells in the brain after stroke, possibly in an IL-10 directed manner." (PMID 26742037, 2016). "Female stroke patients had higher levels of IL-10 compared to males (p = 0.014)." (PMID 26462256, 2015). "IL-10 has been studied in experimental stroke models, and levels are time-dependent." (PMID 26462256, 2015). "After controlling for other known predictors of stroke outcomes in a multivariate analysis, levels of IL-10 were not independently associated with outcomes in females or in males." (PMID 26462256, 2015). "According to our preliminary results, IL-10 measurement may potentially improve the diagnostics of stroke etiology." (PMID 25923658, 2015). "Future studies will need to determine the time course of IL-10 after stroke in both men and women." (PMID 26462256, 2015). "This suggests that higher serum IL-10 levels may reflect factors that interact with sex such as age and stroke severity." (PMID 26462256, 2015). "We only investigated levels at one time point after stroke and may have missed the peak IL-10 response." (PMID 26462256, 2015). "We hypothesized that levels of lipopolysaccharide binding protein (LBP), interleukin-10 (IL-10), IL-6 and C-reactive protein (CRP) are early predictors for the development of stroke-associated infection." (PMID 25613713, 2015). "Interestingly, this increased sympathetic drive induced activated iNKT cells to produce increased levels of anti-inflammatory cytokines such as IL-10, which led to post-stroke immunosuppression." (PMID 26042123, 2015). "IL-10 levels also have been found to differ with stroke etiology." (PMID 26462256, 2015). "Thus, it is likely that the immunosuppressive effect of IL-10 post-stroke affects females differently than males, and this topic merits further investigation." (PMID 26462256, 2015).
Stroke (continued). "After controlling for confounders, IL-10 was not independently associated with mortality or post-stroke functional outcomes in either sex." (PMID 26462256, 2015). "IL-10 is known to confer beneficial effects in several neuroinflammatory disease models, including experimental autoimmune encephalomyelitis, traumatic or excitotoxic spinal cord injuries, stroke, and Parkinson’s disease." (PMID 25404049, 2015). "As the increased level of IL-10 seems to be vascular- and cardioprotective according to the previous literature, IL-10 is not likely to be the predisposing factor for the stroke in our cardioembolic subgroup, either." (PMID 25923658, 2015). "B cells can function as antigen-presenting cells to activate cytotoxic CD8+ T cells, but there is also data to suggest that an IL-10-producing subpopulation of regulatory B cells may limit injury in experimental stroke." (PMID 25477780, 2014). "This may exacerbate neurodegenerative damage, to the detriment of cognitive function, since Tregs are thought to be beneficial after stroke due to their secretion of the anti-inflammatory and neuroprotective cytokine IL-10 into the postinfarct brain." (PMID 25054133, 2014). "Importantly, in humans, upregulation of IL10 in the blood has been correlated with improved outcome in stroke." (PMID 21999375, 2011). "Moreover, patients with low plasma levels (<6 pg/ml) of IL-10 during the first hours after stroke were three times more likely to have worsening neurological symptoms within 48 hours following the stroke." (PMID 19919699, 2009). "Moreover, Tregs secreting cytokine IL-10 have a protective effect on stroke." (PMID 39634770, 2024). "Under pathological conditions such as stroke, astrocytes become reactive, markedly increasing the expression of glial fibrillary acidic protein (GFAP), the hallmark signature of reactive gliosis, in response to intercellular signaling molecules including IL-6, TNFα, TGF-β, INFγ, and IL-10." (PMID 38854014, 2024). "Notably, reduced expression of transcription factors (GATA-3, FoxP3), cytokine IL-10, and elevated mRNA expression of IFN-γ, TNF-α, and inducible nitric oxide synthase (iNOS) have been observed to increase the risk of death from stroke in these patients patients." (PMID 39217407, 2024). "Furthermore, the administration of IL-10 can reduce the post-stroke inflammation in animal models." (PMID 36745280, 2023). "Further, given that in stroke patients, the number of circulating Tregs decreases dramatically post-stroke, investigating whether Tregs and the regulatory factors produced, such as IL-10 or TGF-β, ameliorate resultant neuroinflammation/neurodegeneration after TBI is clearly warranted." (PMID 38162004, 2023). "In addition, a promising lead compound promoting IL-10 activity was provided, confirming that promoting IL-10 expression may be useful to treat AD and stroke." (PMID 35875800, 2022). "In addition, post-ischemic IL-10 gene transfer by adenoviral vector or exogenous IL-10 administration significantly promoted neuroprotection by limiting inflammation in an experimental stroke animal." (PMID 35887140, 2022). "We then evaluated whether gene expression was altered after stroke upon eTc-IL10 treatment." (PMID 36512388, 2022). "Lower levels of IL-10 and IL-33 may also be used to predict post stroke depression." (PMID 35173738, 2022). "Next, we studied whether the IL-10 production from invading immune cells or brain resident cells including microglia, astrocytes, or neurons is decisive for the protective IL-10 effect following stroke." (PMID 34772416, 2021). "Thus, the decreased IL-12 and increased IL-10 release from blood cells might contribute to post-stroke immunodepression." (PMID 31906994, 2020). "Furthermore, the levels of the inflammatory and anti-inflammatory cytokines such as IL-1β, IL-6, and IL-10, at the early stage of stroke might serve as important biomarkers to predict the prognosis for ischemic stroke patients." (PMID 30705764, 2019).